FAM90A7 (family with sequence similarity 90 member A7)
Synonyms: FAM90A7P
Tractability: No criterion of Open Targets' tractability assessment is met for any kind of drug.
Gene: Protein-coding gene on chromosome 8 (7,556,700 to 7,559,712, reverse strand). Ensembl gene ENSG00000285975.
Subcellular location (Human Protein Atlas): Nucleoplasm; Nucleoli
Homologues: Orthologues: mouse Fam90a1b (28% identical), mouse Fam90a1a (27% identical), rat Fam90a1l1 (26% identical). Paralogues in human: FAM90A10 (98% identical), FAM90A16 (97% identical), FAM90A17 (97% identical), FAM90A23 (97% identical), FAM90A9 (97% identical), FAM90A8 (97% identical), FAM90A18 (97% identical), FAM90A19 (97% identical), FAM90A13 (97% identical), FAM90A15 (97% identical), FAM90A24 (97% identical), FAM90A14 (96% identical), and 9 more.